MMP2 (matrix metallopeptidase 2)
Diseases named in the same sentence as MMP2 in open-access papers (continued):
Sharing a sentence is not in itself a finding about the gene and the disease.
tumor (continued). "Endothelial cells constitutively secrete MMP-2, which is required to trigger tumor angiogenesis in vitro and in vivo." (PMID 37237967, 2023). "Analysis of serial patient cerebrospinal fluid (CSF) samples showed an increase in MMP-2 activity in three out of four patients as the tumour progressed." (PMID 37174066, 2023). "Matrix metalloproteinase 2 (MMP2) is overexpressed in many tumors, and high MMP2 levels are associated with tumor metastasis and progression." (PMID 37521428, 2023). "The same increase in MMP2 has been observed in mesenchymal stromal cells stimulated by tumor-derived EV." (PMID 37569393, 2023). "Other CAF-derived molecules, such as the chemokine CXCL12 or the extracellular protease MMP2, have also been shown to promote the proliferation and invasion of tumor cells in diverse cancers." (PMID 37566084, 2023). "The results showed that low expression of CDK5RAP3 significantly promoted tumour proliferation in vivo, while the MMP2 inhibitor reversed this phenomenon." (PMID 35999359, 2023). "MMP2, 3, 9, and 14, derived from CAFs and tumour cells in OSCC, are important enzymes for metastasis; however, their role in ENE development has not been examined." (PMID 36765296, 2023). "In another study, MMP2 inhibitor modulates tumor immune surveillance and enhances the efficacy of immunotherapy by regulating PD-L1." (PMID 36788565, 2023). "These dual‐responsive liposomes enable improved biodistribution and on‐demand release of immune checkpoint inhibitor (ICI) molecules within tumor regions via specific cleavage of tumor regionally secreted MMP‐2 enzymes following injection." (PMID 37560754, 2023). "It increases endothelial cell proliferation and migration, tumour growth in vivo, and remodels the perivascular matrix by increasing levels of proteinases, including matrix metalloproteinases MMP2 and MMP9." (PMID 37446252, 2023). "The enrichment of MMP-2 in the tumor cell region promotes the drug-release effect of the gelatin-based carrier material in the tumor region." (PMID 37025360, 2023). "Through enhanced permeability and retention (EPR), aPD-L1/ICG@NP passively accumulates at the tumor site and is activated to release aPD-L1 in high MMP-2-expressing tumors to block PD-L1 on tumor cells." (PMID 37144580, 2023). "It has been reported that MMP-2 in tumor cells increases the expression of SDF1, leading to increased stem cell tropism toward tumor cells via the SDF1/CXCR4 axis." (PMID 36915092, 2023). "Studies have also shown that a combination of SB-3CT (matrix metallo proteinases=MMP2/9 inhibitor) and docetaxel was more effective in tumor growth inhibition in metastatic cases." (PMID 37461792, 2023). "The enzyme-responsive peptide is cleavable in the presence of MMP2, which is overexpressed in the tumor microenvironment of prostate cancer." (PMID 36986837, 2023). "R300 is specifically released in the tumor on the cleavage of the lipid-peptide shell of the nanoparticles by MMP2, which is commonly overexpressed in tumor vascular endothelia and stroma." (PMID 37122851, 2023). "These are well-known to promote tumor development through tissue remodeling; they secrete proteases, such as matrix metalloproteinase-2 (MMP-2) and matrix metalloproteinase-9 (MMP-9)." (PMID 36986856, 2023). "The matrix metalloproteinase 2 (MMP2) can degrade FBN1, but succinylation of FBN1 on K672 disrupts this interaction with MMP2 in the tumour microenvironment causing an accumulation of FBN1." (PMID 38213532, 2023). "Western blot analysis showed that the expression of MMP2 in tumor cells was significantly increased following pre-treatment with exosomes from two OS cells." (PMID 37990331, 2023). "The finding suggests that there is positive feedback in which MMP2 can activate FAK signaling leading to the upregulation of MMP2 itself in tumor cells." (PMID 36677584, 2023).
tumor (continued). "Mesenchymal cells and fibroblasts in tumor tissue secrete fibroblast growth factor (FGF), chemokine (C-X-C Motif) ligand 12 (CXCL12), and matrix metallopeptidase 2 (MMP2) to enhance tumor cell growth, invasion, and metastasis." (PMID 36909170, 2023). "Given the key roles mediated by MMP2 and MMP9 in tumor metastasis, their association with MALAT1 and ALKBH5 was subsequently investigated." (PMID 37639643, 2023). "EMT promotes tumor metastasis by upregulating or downregulating the expression of epithelial markers such as MMP-2, MMP-9, VEGF, vimentin, E-cad, and N-cad." (PMID 37020791, 2023). "Black tea polyphenols can prevent cancer metastasis by regulating pathways important in the migration of tumor cells involving Matrix Metalloproteinase-2, -7, and -9 (MMP-2, -7, -9)." (PMID 37597078, 2023). "Previous research has suggested that differential glycosylation of EMMPRIN exhibits functional relevance in tumour cells, with the highly glycosylated form being associated with enhanced cell adhesion, cell migration, and MMP-1 and MMP-2 production." (PMID 37174066, 2023). "MMP relative expression levels seem to increase with tumor growth, thus far and many reports have connected greater MMP2 and MMP9 levels to enhancing metastatic cells." (PMID 36700237, 2023). "Areas of MMP-9 and MMP-2 positive staining were also detectable in the tumor cells and fibroblast-like cells." (PMID 37175975, 2023). "MMP2 has the ability to degrade collagen in vascular basement membrane, which is closely related to tumor angiogenesis 54, and its activation state plays a crucial role in angiogenesis." (PMID 37283793, 2023). "After the Gel-N-ICG was degraded by the tumor microenvironment’s overexpressed gelatinase, MMP-2/9, the loaded ICG and NSC were released." (PMID 36986636, 2023). "Tumor tissue analysis revealed significant levels of MMP-2 and MMP-9 expression and their active forms." (PMID 38069361, 2023). "In glioma cells incapable of forming tumor xenografts, FOXM1b overexpression enabled tumor formation in nude mice and promoted invasion through MMP-2 upregulation." (PMID 37174744, 2023). "Based on in vivo investigations, mice treated with melittin-MMP2-LAP recombinant adenovirus had a B16 tumor volume that was around 70% lower than that of control mice." (PMID 38133203, 2023). "Here, we report on the synthesis of MMP-2 cleavable PEGylated CLs, which expose their cationic lipids in response to the upregulated MMP-2 at the tumor microenvironment, resulting in enhanced liposomal uptake and drug delivery to tumor cells and vasculature." (PMID 36910721, 2023). "In mouse skin tumors, luteolin inhibited tumor growth, decreased tumor volume and weight, and suppressed the expression of MMP-2 and MMP-9." (PMID 38248322, 2023). "The elevated expression of MMP2 on tumor cells or stromal cells in the tumor microenvironmen was involved in tumor invasion and progression, with patients often having poorer prognosis." (PMID 36788565, 2023). "Upregulation of PDGF‐D in endometrial cancer cells can lead to tumor metastasis via promoting MMP2/9 expression and EMT." (PMID 37719444, 2023). "MMP2 and MMP9 are strongly expressed in varying malignant tumor tissues and are strongly associated with tumor cell invasion and metastasis." (PMID 36882799, 2023). "Gelatin zymography was used to demonstrate the activation of tumor-secreted proMMP9 by the MT1-MMP/MMP2 axis, thus hydrolyzing the surrounding ECM." (PMID 37653282, 2023). "While in the tumor microenvironment, the MMP-2/9-cleavable peptide linker is cleaved and re-exposes the CPP to enhance cellular uptake." (PMID 37242692, 2023). "STAT3 is a transcription factor that induces MMP-2 expression and is believed to bind directly to the MMP-2 promoter in human tumor cells." (PMID 38020106, 2023). "Overexpression of MMP2/MMP9 after incubation of recipient tumor cells with sEVs from irradiated donor cells is considered one of the main mechanisms of the non-target effects of radiotherapy." (PMID 37109070, 2023).
tumor (continued). "EBA administration significantly impeded BCSC-enriched tumor burden, angiogenesis and distant metastasis while reducing MMP-2/-9 levels in circulating blood in vivo." (PMID 37185776, 2023). "Nanoparticles passively accumulate at the tumor site, and in response to MMP-2, iRGD is released from the nanoparticles, promoting deep tumor penetration of avasimibe." (PMID 37144580, 2023). "In many cancers, MMP2/9 performs an active role in cell proliferation, invasion, and tumor metastasis." (PMID 36765716, 2023). "Among them, MMP2 and MMP9 were significantly associated with tumor immune infiltrates and had good binding affinity with effective ingredients." (PMID 37565919, 2023). "CLTX was isolated from the venom of the death stalker scorpion, and primarily utilizes the matrix metalloprotease-2 (MMP-2) as its receptor, a surface molecule found on a high percentage of glioblastoma cells and a wide variety of other tumours." (PMID 37242495, 2023). "Studies have indicated that SPOCK1 can promote the abnormal activation of MMP-3, MMP-9, and MMP-2, leading to directed migration of tumor cells from the edge of the tumor mass and ultimately inducing ECM remodeling." (PMID 38087364, 2023). "In contrast, the T1 signal enhancement of tumour received MMP‐2 inhibtor is inconspicuous under the same administration dose of probe." (PMID 38264683, 2023). "All investigated tumor‐promoting MMPs were significantly increased in M2‐like macrophages, with MMP2 showing the lowest upregulation in M2‐like macrophages compared to THP‐1 monocytes." (PMID 38037545, 2023). "On the other hand, MMP-2 expression was correlated with tumor size and neovascularization, MMP-9 expression was correlated with hormone receptor status, and stromal cell co-expression of MMP-2 and MMP-9 was significantly associated with tumor size." (PMID 37496657, 2023). "High levels of MMP-2 and MMP-9 have been observed in patients with high-grade GB and high-risk NB and are associated with tumor progression." (PMID 37444498, 2023). "All enrolled patients were on bone-targeting agents at study entry, and it has been shown in vitro that bone-targeting agents (including clodronate, pamidronate and zoledronic acid) can inhibit tumor cell expression of MMP2 and MMP9." (PMID 36765529, 2023). "During cancer metastasis, C-X-C chemokine receptor type 7 (CXCR7) recruits tumor-promoting macrophages (M2) to tumor tissues and upregulated MMP-2/9 expression." (PMID 37766868, 2023). "Studies on RCC with mutated VHL have shown that proinflammatory cytokines (e.g., IL-6, TNF-α, IL-1) and MMP-2 foster tumor spread and are overexpressed in more invasive cell lines." (PMID 36614308, 2023). "Overexpression of ARG2 promoted the MMP2/9 expression, further enhancing tumor cell proliferation, migration, invasion and angiogenesis." (PMID 36817446, 2023). "Anti-PD-1 therapy was administered every 3 days and MMP2 inhibitor was administered daily, and tumor volume was measured every 2 days." (PMID 36788565, 2023). "There is substantial evidence to show that the efficacy of CTX is related to its ability to cross the BBB as well as its high tumor-binding function mediated by the molecular targets namely, chloride channels, MMP-2, annexin A2, and recently, ERα and NRP-1." (PMID 37444498, 2023). "Green tea polyphenol epigallocatechin-3-O-gallate (EGCG) inhibits tumor invasion by directly inhibiting the MMP-2/-9 activity." (PMID 37509062, 2023). "The CXCL5/CXCR2 axis favors migration and invasion in BC cell lines, increasing MMP-2/-9 levels through the PI3K/AKT pathway, and CXCL5 has been linked to tumor grade, muscle invasion, and poor OS." (PMID 36614308, 2023). "MMP2 (gelatinase A) plays a crucial function in tumor growth because of its ability to break down collagen IV found in the basement membrane." (PMID 36700237, 2023).
tumor (continued). "It is important to note the role of the matrix metalloproteinases (MMPs), especially MMP2, as one of the important internal pathological changes of the tumor microenvironment." (PMID 36839771, 2023). "It has been observed that the overexpression and increase in the secretion of MMP-2 and MMP-9 are associated with processes such as invasion, metastasis, and a poor prognosis, resulting in key factors in tumor progression." (PMID 38137922, 2023). "Potential downstream effectors in the signaling pathways involved in AQP1-mediated tumor progression include β-linked protein, Lin-7, FAK, MMP2, MMP9, and histone proteinase B." (PMID 37334171, 2023). "The MMP2-sensitive micelles increased tumor penetration and micellar cargo uptake, according to an in vivo tumor retention trial." (PMID 36986837, 2023). "Nevertheless, higher expressions of some factors were observed by stromal cancer-associated fibroblasts compared with fibroblasts from previous biopsy (MMP-9 and TIMP-3) or to fibroblasts from non-tumor zones of prostatectomy (MMP-2 and TIMP-3)." (PMID 37108185, 2023). "Once NIA-D1@R848 reached tumor sites, it would be decomposed under the overexpressed MMP-2 in the tumor microenvironment, and NIA-PLG, PD-L1 antagonist, and R848 were then released." (PMID 37908727, 2023). "Malignant epithelial cells from the prostatectomy tumor site (C4) showed higher expression of MMP-2, -9, and -11, and TIMP-3 than ECs from the benign biopsy site with future cancer development (C2)." (PMID 37108185, 2023). "IL‐6 induced production of glutathione has been shown to stimulate MBM by triggering MMP‐2 enzymatic activity in the tumour microenvironment." (PMID 37759347, 2023). "SB-3CT promoted both NKG2D/NKG2DL by antagonizing the MMP-2 pathway to block tumor cell immune escape." (PMID 37513483, 2023). "MMP2, 3, and 9 are expressed within the tumour cell cytoplasm, MMP2 and 9 are gelatinases, while MMP3 is a stromelysin." (PMID 36765296, 2023). "At the angiogenic switch, the first step of tumor vascularization, MMP-2 and MMP-9 have been shown to be crucial." (PMID 37228582, 2023). "Decreased THBS2 expression increases the amount of matrix metalloproteinase 2 (MMP2) thereby modulating the extracellular matrix structure, resulting in a morphological change of the tumour." (PMID 36765536, 2023). "This is consistent with previous studies, which have described a high expression of MMP-2 in GB tissues, and tumor cells as its main source." (PMID 37190125, 2023). "Tumour cell invasion of the surrounding stroma with further metastasis can also be mediated by promoting MMP-2, MM-9 and MT1-MMP translation." (PMID 37996927, 2023). "Compared with the unmodified ADENS, the TMSP-modified ADENS showed enhanced cellular uptake, tumor penetration and accumulation via an MMP-2/9-dependent mechanism." (PMID 37242692, 2023). "In a clinical study, a low level of MMP2 is associated with longer mean survival amongst GBM patients, and its increased level is positively associated with increased tumour grades and recurrence." (PMID 37372103, 2023). "Tissue inhibitor of metalloproteinase-2 (TIMP-2) plays a critical role in regulating tumor invasion by modulating the activity of MMP-2." (PMID 38276258, 2023). "Following carboplatin treatment, CAFs increased their expression of numerous MMP genes (Mmp2, Mmp3, Mmp13, Mmp14, Mmp27); proteases involved in the degradation of the tumor-supporting matrix." (PMID 37660083, 2023). "pH/MMP2/temperature triple-sensitive NIL-IM-Lip was elaborately designed for targeted tumour delivery and direction to the LNs." (PMID 37076492, 2023). "Other studies have shown that commonly administered anesthesia during tumor resection also contributes to the enhanced production of MMP-2 and -9, reflective of serum concentrations." (PMID 38067195, 2023).
tumor (continued). "A multifunctional polymeric micelle containing MMP‐2 sensitive peptide for tumor‐targeted co‐delivery of siRNA (si‐survivin) and hydrophobic chemotherapy drugs was designed to enhance the uptake of siRNA and paclitaxel in tumor cells." (PMID 37915127, 2023). "As a result, the correlation between ΔR1 and MMP‐2 contents reveals that the MMP‐2 content inside the tumours can be successfully reflected by the variation of T1 signals." (PMID 38264683, 2023). "PLD-1 produces phosphatidic acid (PA), which is associated with the activation of matrix metalloproteinase-2 (MMP-2), i.e., extracellular matrix proteins directly involved in tumor metastasis." (PMID 36986827, 2023). "In NCI−H23 human NSCLC cells, combination of ionizing radiation and MMP-2 inhibition promoted the killing function of NK−92 natural killer cells to cancer cells, suggesting that MMP-2 suppression is helpful for restoring host anti-tumor immune response." (PMID 37766868, 2023). "Increased levels of secreted MMP-2 would support extracellular-matrix degradation, in turn facilitating tumour cell invasion and metastasis." (PMID 37174066, 2023). "As demonstrated in tumor cells during angiogenesis, CD44 mediates cell surface localization of MMP9 and MMP2 and is thereby also implicated in TGF-β1 activation." (PMID 37894778, 2023). "In the tumor environment, matrix metalloproteinase-2 (MMP-2) is cleaved, removing the masking peptide sequence and exposing the cell-penetrating peptide sequence to interact with the cell membrane." (PMID 36904404, 2023). "Altogether, the MMP-2-cleavable CLs have great potency to improve tumor-targeted drug delivery and cellular/tumor-vasculature uptake which merits further investigation." (PMID 36910721, 2023). "ATP5B overexpression increases extracellular ATP levels through intracellular ATP secretion, activates FAK/AKT/MMP2 signaling, and promotes the proliferation, migration, and invasion of tumor cells." (PMID 38273855, 2023). "In a different study, pinostilbene hydrate suppressed the epithelial-mesenchymal transition and downregulated MMP-2 to prevent tumor cell migration and invasion." (PMID 37228582, 2023). "Previously published research documented that GLE significantly suppressed the number of metastatic tumor-bearing mice, the number of affected organs, and the number of tumor foci as well as the MMP-2 and -9 activities in serum of mice." (PMID 37641070, 2023). "The hydrolysis of gelatin by metalloproteinases (MMP-2) in the tumor environment and release of DOX/DGL enabled the permeation of DOX into the core tumor." (PMID 36850121, 2023). "MMP2, 3, 9, and 14 expression in the tumour nest and CAFs was more profound at the ENE site than in the intranodal component (p < 0.01)." (PMID 36765296, 2023). "In tumor angiogenesis, MMP-2 and MMP-9 have been shown to be critical during the “angiogenic switch”." (PMID 36759828, 2023). "Numerous studies have demonstrated that MMP-2 plays a critical role in tumor cell-mediated extracellular matrix degradation." (PMID 37283793, 2023). "These iMCs displayed CCR1 expression enabling migration along with CCL9 gradient, as well as intense production of matrix metalloproteinases MMP9 and MMP2; therefore, the iMCs promoted tumor invasion." (PMID 37185750, 2023). "At the same time, TAMs and tumour cells can promote angiogenesis by releasing enzymes to generate angiogenesis, such as MMP2, MMP‐7, MMP‐9, MMP‐12 and cyclooxygenase‐2 (COX‐2) to improve the invasiveness and motility of cells." (PMID 35961680, 2023). "A self-assembled polymeric nanoparticle was designed to be directed to tumor tissues via bioorthogonal chemistry, and PEGs on their surfaces were to be cleaved in response to matrix metalloproteinase 2 (MMP2) in TMEs." (PMID 36839734, 2023). "EGCG decreased AsPC-1 xenograft tumor volume, angiogenesis, and metastasis together with downregulation of MMP2, MMP7, MMP9, and MMP12." (PMID 36677584, 2023).